CAMSAP3 (calmodulin regulated spectrin associated protein family member 3)
Description:
Key microtubule-organizing protein that specifically binds the minus-end of non-centrosomal microtubules and regulates their dynamics and organization. Specifically recognizes growing microtubule minus-ends and autonomously decorates and stabilizes microtubule lattice formed by microtubule minus-end polymerization. Acts on free microtubule minus-ends that are not capped by microtubule-nucleating proteins or other factors and protects microtubule minus-ends from depolymerization. In addition, it also reduces the velocity of microtubule polymerization. Required for the biogenesis and the maintenance of zonula adherens by anchoring the minus-end of microtubules to zonula adherens and by recruiting the kinesin KIFC3 to those junctional sites. Required for orienting the apical-to-basal polarity of microtubules in epithelial cells: acts by tethering non-centrosomal microtubules to the apical cortex, leading to their longitudinal orientation. Plays a key role in early embryos, which lack centrosomes: accumulates at the microtubule bridges that connect pairs of cells and enables the formation of a non-centrosomal microtubule-organizing center that directs intracellular transport in the early embryo (By similarity). Couples non-centrosomal microtubules with actin: interaction with MACF1 at the minus ends of non-centrosomal microtubules, tethers the microtubules to actin filaments, regulating focal adhesion size and cell migration. Plays a key role in the generation of non-centrosomal microtubules by accumulating in the pericentrosomal region and cooperating with KATNA1 to release non-centrosomal microtubules from the centrosome. Through the microtubule cytoskeleton, also regulates the organization of cellular organelles including the Golgi and the early endosomes. Through interaction with AKAP9, involved in translocation of Golgi vesicles in epithelial cells, where microtubules are mainly non-centrosomal. Plays an important role in motile cilia function by facilitatating proper orientation of basal bodies and formation of central microtubule pairs in motile cilia (By similarity).
Synonyms: KIAA1543; Nezha; PPP1R80
Tractability: PROTAC: ubiquitination databases record sites on it; its protein half-life has been measured.
Gene: Protein-coding gene on chromosome 19 (7,595,826 to 7,618,352, forward strand). Ensembl gene ENSG00000076826.
Subcellular location: Cytoplasm, cytoskeleton; Cell junction, adherens junction; Cytoplasm; Cytoplasm, cytoskeleton, cilium axoneme; Cytoplasm, cytoskeleton, cilium basal body
Gene Ontology:
Molecular function: actin filament binding; microtubule minus-end binding; protein binding; DNA binding; calmodulin binding; microtubule binding; spectrin binding
Biological process: epithelial cell-cell adhesion; establishment of epithelial cell apical/basal polarity; establishment or maintenance of microtubule cytoskeleton polarity; microtubule anchoring; microtubule cytoskeleton organization; regulation of cell migration; regulation of focal adhesion assembly; regulation of Golgi organization; regulation of microtubule cytoskeleton organization; regulation of microtubule polymerization; regulation of organelle organization; zonula adherens maintenance; cilium movement; DNA replication checkpoint signaling; embryo development ending in birth or egg hatching; protein transport along microtubule; replication fork arrest; neuron projection development
Cellular component: centrosome; cytoplasm; microtubule minus-end; zonula adherens; axoneme; ciliary basal body; motile cilium; replication fork protection complex; adherens junction; cytoskeleton; microtubule cytoskeleton
Genetic constraint (gnomAD): Loss-of-function variants: 33 observed, 86.49 expected, observed/expected ratio (o/e) 0.38, 90% interval 0.29 to 0.51. The synonymous counts are far from expectation, so gnomAD's model fits this gene poorly and the ratio says little. Missense variants: 1,583 observed, 1,574.9 expected, observed/expected ratio (o/e) 1.01, 90% interval 0.96 to 1.05. Synonymous variants: 849 observed, 709.83 expected, observed/expected ratio (o/e) 1.2, 90% interval 1.13 to 1.27.
Homologues: Orthologues: chimpanzee CAMSAP3 (99% identical), macaque CAMSAP3 (98% identical), pig CAMSAP3 (92% identical), dog CAMSAP3 (92% identical), rat Camsap3 (91% identical), mouse Camsap3 (91% identical), guinea pig CAMSAP3 (77% identical), rabbit CAMSAP3 (75% identical), tropical clawed frog camsap3 (54% identical), zebrafish camsap3 (51% identical), zebrafish CAMSAP3 (33% identical), Drosophila melanogaster Patronin (24% identical), and 1 more. Paralogues in human: CAMSAP2 (41% identical), CAMSAP1 (36% identical).
Diseases named in the same sentence as CAMSAP3 in open-access papers:
CAMSAP3 is named in the same sentence as 21 diseases in open-access papers, as found by Europe PMC text mining. Sharing a sentence is not in itself a finding about the gene and the disease. The quoted sentences say what the papers report.
lung carcinoma (7 papers, 2021 to 2025). "CAMSAP3 exhibits oncogenic properties in lung cancer, while CAMSAP1 is associated with immune escape in some tumors." (PMID 41464116, 2025). "CAMSAP3 knockout promotes lung cancer cell senescence‐associated phenotypes and induces G1 cell cycle arrest." (PMID 34724356, 2021). "This study demonstrated that CAMSAP3 knockout promotes lung cancer cell senescence‐associated phenotypes through suppression of ERK/vimentin complex that is required for stabilization of ERK activity." (PMID 34724356, 2021). "Our results demonstrated for the first time the essential role of CAMSAP3 in cellular senescence‐associated phenotypes in human lung carcinoma cells." (PMID 34724356, 2021). "This study is the first to report an intriguing role of CAMSAP3 in lung carcinoma cell senescence‐associated phenotypes via the modulation of p‐ERK/cyclin D1 signaling." (PMID 34724356, 2021). "Gene expression profiling data have shown that lung cancer tissues with low CAMSAP3 expression levels are closely associated with a decreasing overall survival rate of lung adenocarcinoma patients." (PMID 34724356, 2021). "The function of CAMSAP3 on the regulation of cellular senescence‐associated phenotypes in human non‐small cell lung cancer H460 cells were determined in CAMSAP3 deletion (H460/C3ko) cells." (PMID 34724356, 2021). "In addition to our prognostic data concerning lung cancer, emerging evidence suggests a link between CAMSAP3 loss and therapy resistance." (PMID 41381443, 2025). "Knockout of CAMSAP3 promoted invasion and malignant progression of lung cancer and the expression of HIF-1α." (PMID 38880903, 2024). "A recent study showed that acetylated tubulin mediated EMT in lung cancer cells through the CAMSAP3/Akt axis." (PMID 36639650, 2023). "CAMSAP3 protects lung cancer cells from the EMT by inhibiting Akt activity through microtubule regulation, whereas CAMSAP3 deficiency promotes the EMT and stemness maintenance in these cells." (PMID 36355541, 2022). "Consistent with a previous study, we reported that cell proliferation in an attachment condition was decreased in CAMSAP3 knockout lung cancer cells." (PMID 34724356, 2021). "Similar to our finding, p‐ERK appeared to be reduced in the presence of cellular senescence‐like characteristics in CAMSAP3 knockout lung cancer cells." (PMID 34724356, 2021). "We investigated cell growth arrest and cellular senescence‐associated phenotypes using RNA interference to specifically silence CAMSAP3 (siC3) in H460 and A549 cells, another lung carcinoma cell line." (PMID 34724356, 2021). "Moreover, Kaplan-Meier survival analysis revealed shorter overall survival in lung adenocarcinoma patients with low CAMSAP3 levels, implicating the prognostic relevance of CAMSAP3 expression in lung cancer progression." (PMID 41381443, 2025). "This interaction highlights the importance of the NCL/CAMSAP3 relationship in regulating aggressive metastatic and angiogenic tendencies in lung cancer cells, establishing CAMSAP3 as a key suppressor in lung cancer progression by influencing the NCL/HIF‐1α mRNA complex." (PMID 39304978, 2024). "However, the biological role of CAMSAP3 on senescence in human lung cancer remains incompletely understood." (PMID 34724356, 2021). "The CAMSAP family comprises CAMSAP1, CAMSAP2, and CAMSAP3, and we reported that CAMSAP3 maintains the epithelial state of lung cancer‐derived cells, preventing them from epithelial–mesenchymal transition (EMT), which is a form of cell changes associated with cancer progression." (PMID 34724356, 2021). "Our previous study uncovered that CAMSAP3 knockout enhanced migration ability in lung cancer cells." (PMID 34724356, 2021). "Interestingly, gene profiling data revealed that CAMSAP3 expression tends to increase in the early stage and decline in the advanced stage of lung cancer." (PMID 34724356, 2021).
lung carcinoma (continued). "In conclusion, our findings establish CAMSAP3 as a key regulator of EGFR signaling and osimertinib response in NSCLC, highlighting its therapeutic potential for overcoming drug resistance in lung cancer." (PMID 41381443, 2025). "However, the biological role of CAMSAP3 in lung cancer remains largely unknown." (PMID 34724356, 2021).
cyst (3 papers, 2021 to 2024). A sac-like closed membranous structure that may be empty or contain fluid or amorphous material. "Despite this uncertainty, the abnormalities in PKD and Camsap3 mutants are quite different, as cyst formation occurs uniformly over the entire kidney in the former, whereas it is a local event in the latter." (PMID 33712686, 2021). "Unlike the intestinal epithelia, however, CAMSAP3 dysfunction caused organ-level abnormalities in bilateral kidneys—that is, cyst formation in PCTs." (PMID 33712686, 2021). "Thus, CAMSAP3 dysfunction did promote cell proliferation, but this process was not always associated with cyst formation." (PMID 33712686, 2021). "Our study suggests that CAMSAP3-mediated non-centrosomal microtubule organization is important for maintaining the mechanosensitive properties of PCTs, and loss of this system causes regional cyst formation in the kidney." (PMID 33712686, 2021). "It is also important to note that although CGN has also been implicated in organizing the PAN of microtubules in Eph4 cells and regulating cyst morphogenesis, CGN does not interact with CAMSAP3, and CGN-KO mouse tissues do not reveal altered architecture of polarized epithelial cells." (PMID 37013686, 2024).
Hydrocephalus (2 papers, 2021 to 2022). Hydrocephalus is an active distension of the ventricular system of the brain resulting from inadequate passage of CSF from its point of production within the cerebral ventricles to its point of absorption into the systemic circulation. "As previously reported, the global KD mice, Camsap3-KD, were born with smaller bodies along with sub-infertility, hydrocephalus, anosmia or hyposmia, sinusitis, respiratory distress, otitis media, and hearing loss." (PMID 35783105, 2022). "In the Camsap3tm 1a/tm1a mice, the global knockdown (KD) of CAMSAP3 expression is associated with impaired ciliary motion, leading to phenotypes of Primary Ciliary Dyskinesia (PCD), which includes hydrocephalus, subfertility, and impaired mucociliary clearance." (PMID 35783105, 2022). "Even the Camsap3-KD mice, which reduce CAMSAP3 expression through RNA processing without deleting any exons of Camsap3 gene, showed some degree of embryonic lethality, sub-infertility, hydrocephalus, anosmia or hyposmia, sinusitis, respiratory distress, otitis media, and hearing loss." (PMID 35783105, 2022).
Infertility (2 papers, 2022 to 2026). "Knockout (KO) mice of the microtubule minus-end binding protein Camsap3 (calmodulin-regulated spectrin-associated protein 3) exhibited infertility without ovulation despite normal estrous cycles." (PMID 42199928, 2026).
endometrial cancer (1 paper, 2025). Primary or metastatic malignant neoplasm involving the endometrium (mucous membrane that lines the endometrial cavity). "For instance, low CAMSAP3 expression has been associated with more aggressive behavior and poor prognosis in early-stage endometrial cancer, reinforcing its broad role as a resistance driver." (PMID 41381443, 2025).
liver cancer (1 paper, 2020). An epithelial or non-epithelial malignant neoplasm that arises from the liver. "Immunohistochemistry (IHC) tissue microarray data from Human Protein Atlas program database revealed high or medium CAMSAP2 staining intensity in 10 out of 12 liver cancer samples, whereas only 3 out of 12 cases showed medium staining of CAMSAP1 and CAMSAP3." (PMID 32206120, 2020).
microcephaly (1 paper, 2019). A congenital or acquired developmental disorder in which the circumference of the head is smaller than normal for the person's age and sex. "Camsap3 mutation in mice yielded major neuroanatomical defects, including microcephaly and thin corpus callosum." (PMID 31371714, 2019).
Muenke syndrome (1 paper, 2021). Muenke syndrome is a syndromic craniosynostosis with significant phenotypic variability, usually characterized by coronal synostosis, midfacial retrusion, strabismus, hearing loss and developmental delay. "Other examples include a low frequency sensorineural hearing impairment in a mouse model of Muenke Syndrome and a low frequency hearing loss of unknown pathology in Camsap3 mutant mice." (PMID 34597341, 2021).
polycystic kidneys (1 paper, 2021). "These mice also had kidneys with multiple cysts, and their phenotype was indistinguishable from that observed in Camsap3dc/dc mice; notably, heterozygous (Camsap3+/–) mice showed no signs of polycystic kidneys." (PMID 33712686, 2021).
tumor (4 papers, 2021 to 2025). "The functions of this family members in tumors show significant heterogeneity, with CAMSAP1 and CAMSAP2 mainly exerting pro-tumorigenic effects, while CAMSAP3 exhibits tumor suppressor properties." (PMID 41464116, 2025). "Recent studies revealed its critical position in autophagic cell death, with HDAC inhibitors inducing tumor cell death by enhancing CAMSAP3 interactions with acetylated HMGB1." (PMID 41464116, 2025). "The expression of TRAP1 and CAMSAP3 in tumor tissues of dead patients was lower than survival patients." (PMID 38880903, 2024). "Osimertinib reduced tumor volumes in both groups, while the final tumor volume inhibition revealed that CAMSAP3 knockdown significantly increased tumor resistance to osimertinib compared with the control group, confirming the critical role of CAMSAP3 in modulating osimertinib resistance." (PMID 41381443, 2025). "Furthermore, an in vivo tumor xenograft experiment showed that tumor initiation is potentially delayed in CAMSAP3 knockout tumors with the downregulation of p‐ERK and cyclin D1, resulting in a senescence‐like phenotype." (PMID 34724356, 2021). "We hypothesize that, at an early stage, CAMSAP3 expression is upregulated in cancer and promotes tumor initiation." (PMID 34724356, 2021). "Interestingly, the number of cells per field was lower in the CAMSAP3‐deleted group than in the control group, and the tumor necrotic area observed in the H460/C3ko group appeared to increase approximately up to 2‐fold compared with that in the H460/Ctrl group." (PMID 34724356, 2021). "Because CAMSAP3 knockout cells exhibited looser cell‐cell contacts and an enlarged cell size, the tumor dimension measurements might be affected by these cellular characteristics, as similarly observed in the colony formation assay that cell‐cell interactions also influence this parameter." (PMID 34724356, 2021). "However, the H460/C3ko group exhibited a longer latency time‐that is, tumors were detectable only in 12.5% of the mice on day 3 and fully developed on day 21, indicating that CAMSAP3 may play a role in tumor initiation." (PMID 34724356, 2021).
cancer (3 papers, 2021 to 2024). A tumor composed of atypical neoplastic, often pleomorphic cells that invade other tissues. "Recently, calmodulin‐regulated spectrin‐associated protein 3 (CAMSAP3), a minus‐end microtubule‐stabilizing protein, has received increasing attention in cancer cell biology." (PMID 34724356, 2021). "TRAP1 and CAMSAP3 expression was greater in the para-cancerous group than in the cancer group with different prognoses." (PMID 38880903, 2024). "As a fundamental role, CAMSAP3 maintains microtubule stability, and CAMSAP3 depletion contributes to microtubule hyperacetylation, facilitating cancer migration." (PMID 36188577, 2022). "CAMSAP2 and CAMSAP3 are mostly reported concerning microtubule dynamics and organization, providing fundamental anti-cancer drug research and development strategies." (PMID 36188577, 2022). "Furthermore, CAMSAP3 levels decline in advanced‐stage cancer, suggesting that CAMSAP3 functions as an antimetastatic regulatory protein." (PMID 34724356, 2021). "CAMSAP3 is differentially expressed during different cancer stages." (PMID 34724356, 2021). "However, the functions of CAMSAP3 in cancer biology are largely unexplored." (PMID 34724356, 2021). "Besides, a non-centrosomal microtubule minus-end binding protein CAMSAP3 plays a distinct suppressive role on cancer metastasis, unlike other CAMSAPs." (PMID 36188577, 2022).
CAMSAP3 also shares sentences with these, for which no sentence is quoted: Anosmia (1 paper); colorectal carcinoma (1); hepatocellular carcinoma (1); lung adenocarcinoma (1); otitis media (1); primary ciliary dyskinesia (1); Respiratory distress (1); sinusitis (1); small cell lung carcinoma (1); Usher syndrome (1).